GLMN (glomulin, FKBP associated protein)
Description:
[Isoform 1]: Regulatory component of cullin-RING-based SCF (SKP1-Cullin-F-box protein) E3 ubiquitin-protein ligase complexes. Inhibits E3 ubiquitin ligase activity by binding to RBX1 (via RING domain) and inhibiting its interaction with the E2 ubiquitin-conjugating enzyme CDC34. Inhibits RBX1-mediated neddylation of CUL1. Required for normal stability and normal cellular levels of key components of SCF ubiquitin ligase complexes, including FBXW7, RBX1, CUL1, CUL2, CUL3, CUL4A, and thereby contributes to the regulation of CCNE1 and MYC levels (By similarity). Essential for normal development of the vasculature. Contributes to the regulation of RPS6KB1 phosphorylation.
Synonyms: FAP; FAP48; FAP68; VMGLOM; GLML; GVM; FKBPAP
Tractability: PROTAC: ubiquitination databases record sites on it; its protein half-life has been measured.
Gene: Protein-coding gene on chromosome 1 (92,245,788 to 92,299,009, reverse strand). Ensembl gene ENSG00000174842.
Subcellular location (Human Protein Atlas): Cytosol; Nucleoplasm
Pathways (Reactome):
Immune System: Antigen processing: Ubiquitination & Proteasome degradation
Gene Ontology:
Molecular function: hepatocyte growth factor receptor binding; protein binding; signaling receptor binding; ubiquitin protein ligase binding; ubiquitin-protein transferase inhibitor activity
Biological process: cell surface receptor signaling pathway; epigenetic regulation of gene expression; muscle cell differentiation; negative regulation of cell population proliferation; negative regulation of T cell proliferation; positive regulation of cytokine production; positive regulation of interleukin-2 production; positive regulation of phosphorylation; regulation of proteasomal ubiquitin-dependent protein catabolic process; vasculogenesis
Cellular component: Cul2-RING ubiquitin ligase complex; Cul3-RING ubiquitin ligase complex; Cul4A-RING E3 ubiquitin ligase complex; cullin-RING ubiquitin ligase complex
Genetic constraint (gnomAD): Loss-of-function variants: 6 observed, 6.52 expected, observed/expected ratio (o/e) 0.92, 90% interval 0.5 to 1.71. That is too few expected variants to judge how well the gene tolerates losing a copy. Missense variants: 75 observed, 87.01 expected, observed/expected ratio (o/e) 0.86, 90% interval 0.71 to 1.04. Synonymous variants: 22 observed, 30.98 expected, observed/expected ratio (o/e) 0.71, 90% interval 0.51 to 1.01.
Homologues: Orthologues: chimpanzee GLMN (99% identical), macaque GLMN (98% identical), dog GLMN (92% identical), mouse Glmn (86% identical), rat Glmn (85% identical), guinea pig GLMN (80% identical), pig GLMN (74% identical), tropical clawed frog glmn (57% identical), zebrafish glmna (50% identical), zebrafish glmnb (40% identical), Drosophila melanogaster CG30496 (23% identical).
Diseases named in the same sentence as GLMN in open-access papers:
GLMN is named in the same sentence as 13 diseases in open-access papers, as found by Europe PMC text mining. Sharing a sentence is not in itself a finding about the gene and the disease. The quoted sentences say what the papers report.
Venous malformation (2 papers, 2015 to 2022). A vascular malformation resulting from a developmental error of venous tissue composed of dysmorphic channels lined by flattened endothelium and exhibiting slow turnover. "According to our data germline heterozygous variants in GLMN are not only causative of glomuvenous malformations but could be related to both AVMs and venous malformations according to the second somatic hit." (PMID 35807022, 2022). "In addition, inherited venous malformations caused by GLMN and TIE2 mutations were also shown to follow the somatic second hit model." (PMID 25674101, 2015).
Blue rubber bleb nevus syndrome (1 paper, 2021). "Particularly, autosomal dominant pathogenic variants in the GLMN gene (OMIM 138000) are associated with the development of glomuvenous malformations (GVMs) and Blue rubber bleb nevus syndrome (BRBNS) (OMIM 112200) in humans." (PMID 33652974, 2021).
DICER1 syndrome (1 paper, 2025). "This raises the possibility that the GLMN mutation might modify the typical tumor spectrum or severity seen in DICER1 syndrome." (PMID 40918549, 2025).
glomus tumor (1 paper, 2025). A rare benign or malignant mesenchymal neoplasm arising from cells that resemble the modified smooth muscle cells of the glomus body. "In contrast, GLMN mutations are more difficult to detect in isolated glomus tumors." (PMID 40918549, 2025).
lymphoma (1 paper, 2019). A malignant (clonal) proliferation of B- lymphocytes or T- lymphocytes which involves the lymph nodes, bone marrow and/or extranodal sites. "In addition, we wanted to check which isoform, either 48 kDa or 68kDa of GLMN was expressed in the lymphoma cell lines, as the antibody cannot distinguish between both isoforms, FAP48 and FAP68, which have different functions." (PMID 31603917, 2019).
prostate tumors (1 paper, 2022). "The expression of GLMN is upregulated in differentiated prostate tumors." (PMID 36338707, 2022).
pulmonary arterial hypertension (1 paper, 2025). Pulmonary arterial hypertension (PAH) is a group of diseases characterized by mean pulmonary artery pressure >20 mmHg and elevated pulmonary arterial resistance leading to right heart failure. "Glomulin (GLMN) encodes a protein essential for vascular smooth-muscle biology, classically implicated in glomuvenous malformations, yet not previously associated with pulmonary arterial hypertension." (PMID 41133550, 2025).
cancer (2 papers, 2013 to 2024). A tumor composed of atypical neoplastic, often pleomorphic cells that invade other tissues. "In the sample of anaplastic histology, GLMN and NAIP were considered marker genes for primitive vesicle-like cancer cells and endothelium-like cancer cells, respectively." (PMID 38678251, 2024). "Finally, to our knowledge, there are no cancer studies to date reporting on HILS1, GLMN, TRIM27 and BC069781." (PMID 23135352, 2013).
GLMN also shares sentences with these, for which no sentence is quoted: cardiomyopathy (1 paper); chronic GvHD (1); glomuvenous malformation (1); lipodystrophy (1); tumor (1).